INS (insulin)
Diseases named in the same sentence as INS in open-access papers (continued):
Sharing a sentence is not in itself a finding about the gene and the disease.
diabetes (continued). "The present study supports the hypothesis that combining agents with complementary mechanisms—such as insulin-sensitizing, antioxidant, and anti-inflammatory pathways—can improve glycemic control and mitigate complications of diabetes." (PMID 40731781, 2025). "Group 1 compared to group 5 also exhibited higher rates of chronic pulmonary disease requiring long-term medication (15.92% vs 9.03%), current smoking prevalence (20.93% vs 6.62%), diabetes management on insulin therapy (10.05% vs 6.10%) and median BMI higher (28.40 vs 27.94, P < 0.001)." (PMID 40397988, 2025). "In this study, we accessed DNA samples from participants in two completed clinical trials (Diabetes Prevention Trial-Type 1 [DPT-1] and Randomised Diabetes Prevention Trial with Oral Insulin sponsored by TrialNet [TN07]) and sequenced 16 KIR genes in addition to HLA-A, -B and -C genes." (PMID 40835749, 2025). "However, cardiovascular risk factors were comparable between the two groups, including diabetes, insulin use, smoking status, arterial hypertension, hypercholesterolemia, and familial history of coronary artery disease (CAD)." (PMID 40407605, 2025). "While diabetes is a metabolic condition characterized by elevated blood sugar levels due to insufficient insulin or ineffective insulin use, it contributes to cardiovascular complications by damaging blood vessels and nerves that regulate the heart and circulation." (PMID 40708978, 2025). "Although these delivery systems are not yet widely adopted in veterinary medicine, they offer promising translational applications, particularly in dogs with diabetes or among research or high-value animals, where real-time glucose monitoring and precision insulin delivery can be life-saving." (PMID 41012437, 2025). "Hence, stimulating beta cell proliferation provides a compelling therapeutic approach for restoring insulin synthesis and potentially reversing the pathogenesis of diabetes." (PMID 40913218, 2025). "Exenatide treatment in 3xTg-AD mice with streptozotocin (STZ)-induced diabetes not only improved glucose metabolism by elevating plasma insulin and reducing plasma glucose and HbA1c levels but also reduced brain Aβ levels, highlighting its potential benefit in managing AD associated with T2D." (PMID 41226780, 2025). "Importantly, patients who demonstrated improved glycemic outcomes were more likely to have sustained their insulin regimens, underscoring the critical role of insulin in diabetes management during crises." (PMID 40700264, 2025). "Additionally, diabetes-induced insulin resistance in the brain can disrupt insulin signaling pathways, which are crucial for maintaining neuronal health and synaptic plasticity." (PMID 41268302, 2025). "Patients with diabetes and prior MI were likely to be on insulin (44.2 vs. 36.2%, p = 0.02)." (PMID 38717480, 2025). "Moreover, the high expression of miR-139 is also associated with the upregulation of proinflammatory factors, which affect the function of pancreatic β cells and their ability to secrete insulin, further exacerbating diabetes." (PMID 39859466, 2025). "For example, in a recent case report of a patient with poorly controlled insulin-requiring diabetes mellitus, intravenous insulin infusion alone effectively lowered triglyceride levels from greater than 11,000 mg/dL to less than 1000 mg/dL over a four-day hospitalization." (PMID 39958046, 2025). "The insulin therapy represents a proved risk factor by itself to increase the fracture risk, and, by excluding it, we intended to capture the essence of the diabetes, not of the associated medication." (PMID 40804864, 2025). "It accounts for approximately 96% of all diabetes cases and is characterized by (a) non-autoimmune, progressive loss of adequate insulin secretion by pancreatic β-cells within the islets of Langerhans, (b) IR, and (c) MetS." (PMID 41614828, 2025).
diabetes (continued). "This trend persisted after age and sex (Model 2) were adjusted for and remained consistent after social history, comorbidities (Model 3), and diabetes‐specific factors (e.g., use of ≥ 3 oral antidiabetic agents, insulin and duration of diabetes) were adjusted for (Model 4)." (PMID 41351230, 2025). "For insulin‐treated people with diabetes, digital diabetes management tools have become a relevant therapy component to improve patients’ self‐management and ultimately diabetes‐related health outcomes." (PMID 41497476, 2025). "Insulin and glucose analyses included adjustments for diabetes status and multiple testing." (PMID 40045464, 2025). "Additionally, diabetes, being a metabolic disease, is often accompanied by high insulin levels and hyperglycemia, leading to endothelial dysfunction, which increases the likelihood of hypertension and all-cause mortality." (PMID 40303616, 2025). "On the second day of life, the patient was diagnosed with diabetes and treated with insulin." (PMID 41153775, 2025). "Recent evidence, however, shows the ability of Bcl-2 and Bcl-xL to protect human β-cells without impairing insulin release, introducing a promising avenue for β-cell-specific therapies aimed at preventing β-cell loss during diabetes progression." (PMID 39857806, 2025). "Intact insulin signaling is required for diabetes remission induced by the central action of FGF1." (PMID 41072794, 2025). "By reducing oxidative stress and inflammatory signalling, chlorophyll derivatives could help preserve insulin signalling pathways and promote metabolic homeostasis, thereby offering a multifaceted therapeutic approach for diabetes management." (PMID 40871679, 2025). "Diabetes and metabolic syndrome: In individuals with diabetes or metabolic syndrome, postprandial insulin excursions may be pronounced and could lower the threshold for TPP attacks in the setting of untreated thyrotoxicosis." (PMID 41523487, 2025). "Consequently, limited evidence remains regarding the effectiveness of health management mobile apps specifically designed for patients with type 2 diabetes mellitus (T2DM) initiating basal insulin (BI)." (PMID 39694849, 2025). "As age is a known factor in brain atrophy, cognitive decline, and changes in metabolic markers such as insulin resistance, cholesterol levels, and kidney function, it is crucial to control for or examine its impact in studies involving brain integrity and diabetes." (PMID 40822944, 2025). "Patients and parents have been reported to have significant demands for health education regarding insulin, oral hypoglycemic drugs, and the most recent developments in diabetes care, such as continuous glucose monitors, islet cell transplantation, and artificial pancreas." (PMID 39961987, 2025). "In Europe, the EMA granted marketing authorization for sotagliflozin in April 2019 for use as an adjunct to insulin therapy to improve glycemic control in adults with type 1 diabetes mellitus; but on 22 March 2022, the European Commission withdrew the marketing authorization in the European Union." (PMID 41012462, 2025). "Many patients with diabetes are on medications like metformin, insulin, or SGLT2 inhibitors." (PMID 40585493, 2025). "Conversely, those with non-insulin-treated diabetes may be under-monitored or under-treated, allowing silent cardiac remodelling to progress." (PMID 41153651, 2025). "Studies have demonstrated that advanced glycation end products (AGEs) are glycosylatic and oxidative products of proteins and lipids, and are crucial in the development of diabetes, leading to inflammation, oxidative stress, cell apoptosis and insulin resistance." (PMID 41463300, 2025). "This narrative review focuses on these non-insulin diabetes medicines." (PMID 40651878, 2025). "Furthermore, insulin resistance related to diabetes directly impacts brain tissue, which possesses its own insulin-signaling pathway that is essential for memory formation and synaptic activity." (PMID 41008348, 2025).
diabetes (continued). "In an in vitro cell study, both cis and trans C16:1n-7 stimulated insulin secretion through the G protein-coupled receptor, which may be primarily involved in the pathogenesis of type 2 diabetes mellitus (T2DM)." (PMID 40507176, 2025). "In diabetes-spectrum phenotypes, where stress-axis and neuroenergetic responses to stimulation vary, genetic moderators might also help explain who expresses insulin-independent glucose disposal or neurometabolic signatures after anodal dosing." (PMID 41302978, 2025). "However, persistent ER stress can lead to β cell death, significantly reducing the functional β cell population necessary for insulin secretion, an issue highly relevant in the context of diabetes." (PMID 40076814, 2025). "Additionally, HIIT has been found to enhance liver metabolism, reduce inflammation, and improve insulin signaling pathways in type 2 diabetes mellitus mice, indicating its effectiveness in addressing lipid metabolism disorders and inflammation in the liver." (PMID 40530242, 2025). "If successful, alginate-based insulin delivery systems could revolutionize the way diabetes is treated, providing more convenient, efficient, and less invasive options for patients around the world." (PMID 40352348, 2025). "In recent years, an increasing number of studies have demonstrated that the gut microbiota and their metabolites play a crucial role in the development of diabetes through altering the intestinal mucosal barrier, influencing insulin secretion, and body immune regulation." (PMID 40533747, 2025). "Over the past century, insulin has been a cornerstone therapy for diabetes mellitus." (PMID 40036884, 2025). "Plants used for “hot” diabetes may possess anti-inflammatory effects that protect pancreatic beta cells and improve insulin function." (PMID 41311837, 2025). "The multivariate logistic regression is divided into 2 rounds to avoid overfitting of the model, marked with the hard line in between—round 1 consists gender, employment in working age, and diabetes duration and round 2 consists HbA1c, insulin delivery, and well-being." (PMID 40846321, 2025). "Additionally, previous investigations showed that SchB can inhibit the onset of diabetes by enhancing insulin secretion." (PMID 40703755, 2025). "Participants on ‘metformin combined with other diabetes medications’ were most likely to use gliclazide, followed by insulin and sitagliptin and had lower HDL and were more likely to have hypertension and polypharmacy and to use statins, compared to the other groups." (PMID 40097879, 2025). "EAAs are also involved in insulin and glucagone regulation in diabetes management, but only few reports investigate their possible implication as dipeptidyl peptidase-IV (DPP-IV) inhibitors and their effect on the stability and secretion of enteroendocrine hormones." (PMID 40871634, 2025). "Moreover, berberine stimulates insulin secretion and ameliorates insulin resistance through multiple pathways, demonstrating protective effects against diabetes complications." (PMID 40864768, 2025). "The key difference between studies lies with all participants having diabetes and attending a tertiary Diabetes Centre enabling timely insulin and glucose‐lowering medication adjustments during clinic visits, aligned with reduced caloric or nutrition advice (e.g. low carbohydrate)." (PMID 39511718, 2025). "Knowledge overall percentage regarding diabetes and insulin." (PMID 41306599, 2025). "Together, these findings suggest that once-weekly insulins could redefine insulin-based management strategies in diabetes, combining clinical efficacy with a reduced treatment burden." (PMID 40937414, 2025). "Studies are investigating whether the immunomodulatory properties of GMSCs can help preserve islet function in diabetes, or if certain OMSCs can be differentiated into insulin-producing cells." (PMID 41007215, 2025).
diabetes (continued). "Moreover, Sangzhi alkaloids (SZ-A), derived from white mulberry twigs, have been shown to promote insulin secretion, protect β-cell function, and prevent β-cell dedifferentiation and apoptosis, making them a promising target for diabetes treatment." (PMID 41007291, 2025). "Understanding the mechanisms that enable islet plasticity during pregnancy could inform the development of pharmacotherapies to enhance insulin secretion, offering potential novel strategies for diabetes management." (PMID 40691142, 2025). "For example, insulin, a biotech drug, is essential for individuals with diabetes." (PMID 40917652, 2025). "Hence, an ideal therapeutic candidate for diabetes treatment and management should aid in metabolic regulation, significantly impact insulin secretion and sensitivity and appetite regulation, and reduce immune system inflammation." (PMID 40806100, 2025). "Hypoglycemia is the most frequent acute complication in individuals with insulin treated diabetes and may limit the achievement of glycemic control." (PMID 40671052, 2025). "Furthermore, reactive oxygen species (ROS) generated due to the immune response also further disrupt insulin signaling and damage tissues, leading to the manifestation of Diabetes Mellitus." (PMID 40136728, 2025). "After adjusting for multimorbidity, the differences in mortality risk between persons treated with "insulin only" and those without diabetes narrowed, underlining the important role of comorbid conditions in outcomes." (PMID 41350985, 2025). "Conventional liposomes, composed of phospholipid bilayers, are biocompatible, can encapsulate both hydrophilic and lipophilic drugs, and protect therapeutics from enzymatic degradation, making them suitable for delivering insulin, curcumin, silibinin, or lycopene in diabetes, obesity, and NAFLD." (PMID 41294602, 2025). "The administration of low and high doses of insulin improved the diabetes-induced changes." (PMID 40348751, 2025). "This difference may be related to the fact that the diabetes-specific ONS group included more patients receiving insulin treatment, which could indicate a more advanced stage of diabetes mellitus." (PMID 41156461, 2025). "Impaired insulin action leads to hyperglycemia, a major factor in diabetes mellitus." (PMID 40666490, 2025). "Additionally, the EtAc fraction of Ficus lutea leaf extract, rich in polyphenols, exhibited potent α-glucosidase inhibitory activity and enhanced insulin secretion, highlighting the therapeutic potential of such bioactive compounds in diabetes management." (PMID 40463898, 2025). "In our case, the patient was on a basal bolus insulin regimen for her poorly controlled diabetes." (PMID 40726866, 2025). "Interestingly, rs10767664 has also been implicated in metabolic processes, with reports linking it to diabetes mellitus, insulin resistance and insulin levels." (PMID 40806241, 2025). "In diabetes, hyperglycemia may be caused either by inadequate insulin secretion (T1DM), development of insulin‐resistant tissues (T2DM), or combined conditions." (PMID 39803296, 2025). "Insulin, isolated in 1921, remains a landmark example, revolutionizing diabetes care." (PMID 40507941, 2025). "Type 1 diabetes is characterized by a total insulin deficiency in which those affected develop ketoacidosis, which can lead to coma that can lead to death if insulin is not administered." (PMID 40649704, 2025). "Insulin-treated mice reflected the same trend as the diabetes group." (PMID 41158127, 2025). "For individuals who manage diabetes with Insulin or sulfonylurea, dose adjustments might be needed to reduce the risk of hypoglycemia." (PMID 41405657, 2025). "In recent years, decision coaches have been instrumental in supporting patients with chronic conditions, such as diabetes, assisting them in understanding insulin administration methods and weighing potential risks and benefits through personalized decision-making support." (PMID 40927185, 2025).
diabetes (continued). "Underserved communities with diabetes also have higher HbA1cs, diabetes distress, and mortality rates and lower utilization of new therapeutic approaches and technologies including insulin pumps and continuous glucose monitoring (CGM) systems, which can improve glycemic outcomes." (PMID 40678170, 2025). "Likewise, metabolic disorders including diabetes mellitus were common, supporting emerging data that link systemic inflammation and hypoxia-induced insulin resistance to the metabolic complications of COPD." (PMID 41531616, 2025). "Implantation of these tissues, which can be engineered to secrete insulin-sensitizing factors, could help restore cardiac function and improve clinical outcomes in patients with IR and diabetes." (PMID 40801620, 2025). "Reduced cognitive function may limit self-management capabilities, making a comprehensive understanding of diabetes management particularly important for healthcare personnel supporting older adults who use insulin." (PMID 41350985, 2025). "In the NOD mouse model of spontaneous diabetes, the B:9–23 peptide of the insulin B chain contains at least one critical epitope; notably, mice expressing insulin molecules with a single amino acid mutation (alanine instead of tyrosine at position B16) are fully protected from the disease." (PMID 39931050, 2025). "In contrast, other diabetes treatments, such as glucagon-like peptide-1 agonists (GLP1a), may offer protective effects against PD progression by modulating insulin signaling pathways." (PMID 40422213, 2025). "The CDCES team used their competencies established with CDCES certification to help families interpret the data from the CGM and to recommend insulin dose changes along with behavior changes and diabetes education to assist the youth in meeting glycemic targets." (PMID 41283065, 2025). "Interestingly, a macroautophagy-independent lysosomal degradation of newly formed insulin granules has been reported in different model systems of diabetes including human origin (β cell lines, human and mouse pancreatic islets as well as diabetic mice)." (PMID 39996055, 2025). "Type 2 diabetes mellitus (T2DM) is a common chronic metabolic disorder characterized primarily by high blood sugar, whose core pathogenesis includes insulin resistance and the subsequent functional deficiency of pancreatic β-cells, which can lead to various serious complications over the long term." (PMID 41488105, 2025). "The MiniMedTM 780G system is an advanced insulin pump system, designed for diabetes management." (PMID 39470803, 2025). "Additionally, Incretin-based therapies potentiate glucose-dependent insulin secretion and refine glycaemic control in individuals with diabetes mellitus." (PMID 41190158, 2025). "Diabetes is a common chronic disease managed with various devices, including blood glucose meters, blood ketone meters, continuous glucose monitors (CGMs), and insulin pumps." (PMID 40152409, 2025). "Variations in diabetes progression, glycaemic control, and patient demographics may influence the efficacy of insulin treatment on bone outcomes." (PMID 40564223, 2025). "Furthermore, injection of an adenovirus expressing recombinant betagenin or the betagenin synthetic peptide into mice with STZ-induced diabetes reduced their hyperglycemia and increased their β-cell mass, which likely increased insulin secretion." (PMID 39826690, 2025). "Notably insulin dose adjustment was left to the discretion of the participant with diabetes and their treating clinician." (PMID 41285865, 2025). "I worry that people will know I have diabetes if I am on insulin treatment." (PMID 40242444, 2025). "Although CGM‐based targets have been proposed for all people with diabetes, those specific to T2D have focused on people on intensive insulin therapy and evidence‐based CGM targets specifically for individuals with T2D on non‐intensive therapy are an unmet need." (PMID 39676327, 2025).